DNAJC13 (DnaJ heat shock protein family (Hsp40) member C13)
Description:
Involved in membrane trafficking through early endosomes, such as the early endosome to recycling endosome transport implicated in the recycling of transferrin and the early endosome to late endosome transport implicated in degradation of EGF and EGFR. Involved in the regulation of endosomal membrane tubulation and regulates the dynamics of SNX1 on the endosomal membrane; via association with WASHC2 may link the WASH complex to the retromer SNX-BAR subcomplex.
Synonyms: KIAA0678; RME8; PARK21
Tractability: Antibody: UniProt places it where antibodies can reach, with high confidence; its Gene Ontology location is reachable by antibodies, with high confidence. PROTAC: ubiquitination databases record sites on it; its protein half-life has been measured.
Gene: Protein-coding gene on chromosome 3 (132,417,502 to 132,539,032, forward strand). Ensembl gene ENSG00000138246.
Subcellular location: Early endosome; Early endosome membrane; Endosome membrane
Subcellular location (Human Protein Atlas): Vesicles; Cytosol
Pathways (Reactome):
Immune System: Neutrophil degranulation
Gene Ontology:
Molecular function: protein binding
Biological process: endosome organization; osteoblast differentiation; regulation of early endosome to late endosome transport; regulation of endocytic recycling; receptor-mediated endocytosis
Cellular component: early endosome; early endosome membrane; endosome membrane; extracellular exosome; lysosomal membrane; membrane; WASH complex; azurophil granule membrane; plasma membrane; secretory granule membrane
Genetic constraint (gnomAD): Loss-of-function variants: 47 observed, 224.77 expected, observed/expected ratio (o/e) 0.21, 90% interval 0.17 to 0.27. The upper end of that interval is the gene's LOEUF score, 0.27, which puts it in group 1 of 6, group 1 being the genes least tolerant of losing a copy. Missense variants: 1,929 observed, 2,382.6 expected, observed/expected ratio (o/e) 0.81, 90% interval 0.78 to 0.84. Synonymous variants: 742 observed, 808.25 expected, observed/expected ratio (o/e) 0.92, 90% interval 0.86 to 0.98.
Homologues: Orthologues: chimpanzee DNAJC13 (99% identical), macaque DNAJC13 (98% identical), dog DNAJC13 (98% identical), pig DNAJC13 (98% identical), mouse Dnajc13 (97% identical), guinea pig DNAJC13 (97% identical), rabbit DNAJC13 (96% identical), rat Dnajc13 (96% identical), tropical clawed frog dnajc13 (88% identical), Drosophila melanogaster Rme-8 (50% identical), Caenorhabditis elegans rme-8 (46% identical). Paralogues in human: DNAJC16 (6% identical), DNAJC10 (5% identical), DNAJC2 (5% identical), DNAJC1 (5% identical), DNAJC21 (5% identical), DNAJC11 (4% identical), DNAJC17 (4% identical), DNAJC14 (4% identical), DNAJC7 (4% identical), DNAJC3 (4% identical), DNAJC18 (3% identical), DNAJC25 (3% identical), and 8 more.
Diseases named in the same sentence as DNAJC13 in open-access papers:
DNAJC13 is named in the same sentence as 20 diseases in open-access papers, as found by Europe PMC text mining. Sharing a sentence is not in itself a finding about the gene and the disease. The quoted sentences say what the papers report.
Parkinson disease (18 papers, 2014 to 2025). A progressive degenerative disorder of the central nervous system characterized by loss of dopamine producing neurons in the substantia nigra and the presence of Lewy bodies in the substantia nigra and locus coeruleus. "Mutations of DnaJ Heat Shock Protein Family Member C13 (DNAJC13) are associated with Parkinson's disease (PD) 57-60." (PMID 40860157, 2025). "Both familial PD due to VPS35 and DNAJC13 mutations present with typical dopa-responsive parkinsonism due to the loss of dopaminergic neurons in the midbrain; however, aS-positive Lewy bodies only appear in the latter." (PMID 38886344, 2024). "DNAJC13, for example, is reported to be involved in endosome trafficking, and it has been closely linked to Parkinson’s disease." (PMID 29253856, 2017). "One of the rare Parkinson‐associated genes is DNAJC13, coding for an endosome‐associated protein." (PMID 40717240, 2025). "Cell biological studies have linked the DNA-J domain Hsc70 co-chaperone RME-8/DNAJC13 to endosomal coat protein regulation, while human genetics studies have linked RME-8/DNAJC13 to neurological disease, including Parkinsonism and Essential Tremor." (PMID 36909501, 2023). "More recently additional quality control genes/mutations have been reported linked for Parkinsonism, including DNAJC6, DNAJC13, VPS35 and ATP6AP2." (PMID 25170892, 2014). "Finally, autosomal dominant coding mutations in DNAJC13, coding for RME-8, have been reported in monogenic forms of Parkinson's disease." (PMID 34897416, 2021). "In contrast, the overexpression of the Parkinson’s disease-associated mutant DNAJC13(N855S) did not enhance autophagy." (PMID 32322926, 2021). "Newly reported genes for dominant Parkinson’s disease are DNAJC13, CHCHD2, andTMEM230." (PMID 28733970, 2017). "WES has become the fastest method for the identification of novel genes in parkinsonism, contributing to the discoveries of FBXO7, WRD45, DNAJC6, DNAJC13, ATP6AP2 and SYNJ1 in recent years." (PMID 25061481, 2014).
Parkinsonism (6 papers, 2014 to 2025). Characteristic neurologic anomaly resulting from degeneration of dopamine-generating cells in the substantia nigra, a region of the midbrain, characterized clinically by shaking, rigidity, slowness of movement and difficulty with walking and gait. "Several other vacuolar protein sorting receptors, such as VPS35, DNAJC26 (GAK) and DNAJC13 (RME-8) are also implicated in monogenic parkinsonism or PD risk." (PMID 38559229, 2024).
breast carcinoma (4 papers, 2015 to 2026). "We also observed a correlation between DNAJC13 expression and macrophage infiltration in human breast cancer, suggesting a clinically relevant association and a potential role in shaping the tumor immune microenvironment." (PMID 41601654, 2026). "Interestingly, high DNAJC13 expression was significantly associated with poor overall survival in breast cancer (BRCA, p=0.045), and colon adenocarcinoma (COAD, p=0.008), while the association is not statistically significant in melanoma (SKCM, p = 0.21)." (PMID 41601654, 2026). "DNAJC13 promoted breast cancer progression, and the overexpression of DNASE1L3 was a good prognostic index for liver cancer and renal cancer." (PMID 33592580, 2021). "The primary role of DNAJC13 is in early endosome transportation, and in ERBB2 positive breast cancers has been implicated in the trafficking of epidermal growth factor receptor (EGFR) to the plasma membrane." (PMID 30578123, 2019). "Analysis of the Cancer Cell Line Encyclopedia (CCLE) revealed a positive correlation between DNAJC13 and CD47 expression across multiple cancer cell lines, including breast cancer, melanoma, and colon cancer." (PMID 41601654, 2026). "Mir-193b decreases in breast cancer cells, which allows the expression of its target genes DNAJC13 and RAB22A, and promotes breast cancer progression." (PMID 26347258, 2015).
Cirrhosis (1 paper, 2022). A chronic disorder of the liver in which liver tissue becomes scarred and is partially replaced by regenerative nodules and fibrotic tissue resulting in loss of liver function. "We conclude that the faulty functionality of neutrophils may be due to the autophagy proteins, i.e., DNAJC13, AHSG, TMSB4X, PROS1, and SERPINA3, which can be used as therapeutic targets in decompensated cirrhosis patients with sepsis." (PMID 35681439, 2022). "Proteomic analysis revealed that faulty functionality of neutrophils may be due to the autophagy proteins i.e., DNAJC13, AHSG, TMSB4X, PROS1 and SERPINA3, which can be used as therapeutic targets in decompensated cirrhosis patients with sepsis." (PMID 35681439, 2022).
Dystonia (1 paper, 2025). An abnormally increased muscular tone that causes fixed abnormal postures. "Among the most significant genetic links are the genes LINGO1, HTRA2, and DNAJC13, which have also been implicated in dystonia." (PMID 40731814, 2025). "Therefore, while LINGO1, HTRA2, and DNAJC13 remain important candidates linking ET, PD, and dystonia, definitive evidence supporting their direct contribution to PD risk is still lacking and requires further investigation." (PMID 40731814, 2025).
meningioma (1 paper, 2020). A generally slow growing tumor attached to the dura mater. "Six potentially pathogenic mutations in PHRF1, ZC3H12B, H2AFV, DNAJC13, DNAH8, SCN2A were non-recurrent; however, given the modest sample size it is difficult to fully evaluate the importance of these variants in the meningioma progression." (PMID 32724039, 2020).
Sepsis (1 paper, 2022). Sepsis is defined as life-threatening organ dysfunction caused by a dysregulated host response to infection. "Expression of TMSB4X was found to be significantly increased in sepsis (p = 0.038) compared to HC and DNAJC13 and AHSG were found to decrease in sepsis compared to w/o sepsis." (PMID 35681439, 2022).
stomach cancer (1 paper, 2019). "In this context, DNAJC13 is seen as a potential therapeutic target, whereas the situation is reversed in stomach cancer; the enriched gene sets for the DNAJC13low phenotype primarily included cell redox homeostasis and those involved in mitochondrial complexes and metabolism." (PMID 30578123, 2019).
neurodegenerative disease (5 papers, 2019 to 2023). A disorder of the central nervous system characterized by gradual and progressive loss of neural tissue and neurologic function. "Indeed, several PD-linked gene mutations or polymorphisms (DNAJC13/RME-8, VPS35, ATP13A2, ATP6AP2, RAB7L1, GBA, GAK, LRRK2) interrupt protein trafficking and degradation via the endosomal pathway, highlighting the importance of the endosomal pathway in the progression of neurodegenerative disease." (PMID 31293375, 2019). "Our results connecting RME-8/DNAJC13 to ALR and autophagy provide a potential mechanism by which RME-8/DNAJC13 could influence neuronal health and the progression of neurodegenerative disease." (PMID 36909501, 2023).
cancer (1 paper, 2026). A tumor composed of atypical neoplastic, often pleomorphic cells that invade other tissues. "Additional experiments in human cancer cells and investigation of direct molecular interactions between DNAJC13 and CD47 trafficking machinery would strengthen the translational potential of these findings." (PMID 41601654, 2026). "We established DNAJC13 knockout (KO) cell lines in three different murine cancer models (EMT6, MC38, and B16F10A) using CRISPR-Cas9–mediated gene editing." (PMID 41601654, 2026). "Given the established role of the CD47–SIRPα axis in enabling tumor immune evasion by suppressing macrophage phagocytosis, we next investigated whether DNAJC13 influences macrophage infiltration in human cancers." (PMID 41601654, 2026). "The context-dependent prognostic impact of DNAJC13 may reflect its diverse cellular functions and the complexity of tumor microenvironments across different cancers." (PMID 41601654, 2026).
tumor (1 paper, 2026). "To experimentally validate the functional consequence of DNAJC13 loss on tumor–macrophage interaction, we performed macrophage co-culture assays to directly assess phagocytosis efficiency." (PMID 41601654, 2026). "To further characterize the biological effects of DNAJC13 loss in tumors, we performed immunohistochemistry (IHC) on harvested tumor tissues to evaluate cell proliferation and apoptosis." (PMID 41601654, 2026). "In addition, further studies with detailed immune profiling will help delineate how DNAJC13 loss modulates macrophage subsets and other immune cell populations in the tumor microenvironment." (PMID 41601654, 2026). "Together, these results demonstrate that loss of DNAJC13 sensitizes tumor cells to macrophage-mediated phagocytosis, likely by disrupting CD47-dependent inhibitory signaling, and reinforces the functional relevance of DNAJC13 as a modulator of innate immune evasion." (PMID 41601654, 2026). "Furthermore, in co-culture assays with macrophages, DNAJC13-deficient tumor cells exhibited increased susceptibility to phagocytosis, supporting a functional role for DNAJC13 in innate immune evasion." (PMID 41601654, 2026). "Together, these findings indicate that DNAJC13 contributes to tumor immune evasion through regulation of CD47 surface abundance." (PMID 41601654, 2026). "Subcutaneous tumors were established using the three cell lines, and tumor growth was monitored in mice bearing vector control, DNAJC13 knockout, and CD47 knockout tumors." (PMID 41601654, 2026). "DNAJC13 emerged as the top hit across all three murine tumor models (B16, MC38, EMT6), suggesting a robust and lineage-independent role in modulating CD47 levels." (PMID 41601654, 2026). "Further investigation using larger and more homogeneous clinical cohorts will be necessary to clarify the prognostic and mechanistic roles of DNAJC13 in distinct tumor types." (PMID 41601654, 2026). "To further validate the functional role of DNAJC13 in regulating tumor immune evasion, we performed in vivo studies using immune-competent mice." (PMID 41601654, 2026). "Loss of DNAJC13 may lead to CD47 internalization or degradation, rendering tumor cells more susceptible to innate immune clearance." (PMID 41601654, 2026). "Interestingly, despite the well-established role of CD47 in suppressing innate immune clearance, we did not observe significant tumor growth delay in mice bearing CD47- or DNAJC13-deficient tumors in the absence of therapeutic intervention." (PMID 41601654, 2026). "Finally, we verify that DNAJC13-knockout decrease tumor burden when treated with CD47 blockade." (PMID 41601654, 2026). "Given our findings that DNAJC13 knockdown enhances macrophage-mediated phagocytosis in vitro, we hypothesized that DNAJC13 expression may influence patient prognosis by modulating anti-tumor immune responses in vivo." (PMID 41601654, 2026). "In the absence of treatment, tumor growth was comparable among all three groups, indicating that neither CD47 nor DNAJC13 knockout alone significantly suppresses tumor progression in vivo." (PMID 41601654, 2026).
DNAJC13 also shares sentences with these, for which no sentence is quoted: anemia (1 paper); colon adenocarcinoma (1); colon cancer (1); essential tremor (1); infection (1); liver cancer (1); melanoma (1); neurological disease (1); renal carcinoma (1).